DDR2 (discoidin domain receptor tyrosine kinase 2)
Diseases named in the same sentence as DDR2 in open-access papers (continued):
Sharing a sentence is not in itself a finding about the gene and the disease.
lung carcinoma (38 papers, 2007 to 2025). "Another study on lung cancer cells carrying “gain-of-function” DDR2 mutations reported that dasatinib demonstrated a very promising therapeutic effect." (PMID 36909198, 2023). "Mutations in NTRK1 and DDR2, which encode tyrosine kinase receptors, have been reported in lung cancer." (PMID 36499051, 2022). "Another study on lung cancer cells harboring “gain-of-function” mutations of DDR2 reported compound 1 to demonstrate a highly promising therapeutic efficacy." (PMID 34207360, 2021). "DDR2 mutations are associated with increased sensitivity to dasatinib, and the clinical activity of dasatinib in lung cancer is being evaluated in numerous clinical trials." (PMID 26373952, 2015). "It is possible that the DDR2 gene mutation was detected in squamous cell component of lung cancer and KRAS gene mutation was detected in adenocarcinoma component of this malignancy." (PMID 25173530, 2014). "Discoidin domain receptor 2 (DDR2) has recently been identified as a possible lung cancer driver, and was associated with the SFK, HCK in clusters derived from all three of these embeddings." (PMID 23300999, 2013). "We must therefore conclude that if these recently reported DDR1 and DDR2 mutations are valid, then their prevalence must be much lower in the general lung cancer population than expected." (PMID 17299390, 2007). "Indeed, some mutations have been identified in DDR1 and DDR2 throughout their structures, but the impact of mutations has been studied mainly for DDR2 and more particularly in lung cancer." (PMID 33917302, 2021). "However, the clinical application was limited by toxicity, and a more selective DDR2 inhibitor compounded with an SRC inhibitor was developed and demonstrated enhanced suppression of DDR2-mutated lung cancer cell lines." (PMID 27793038, 2016). "In addition, using nilotinib, we confirm that DDR2 kinase activity is required for SHP-2 phosphorylation, as described in lung cancer expressing DDR2 with mutations in the kinase domain." (PMID 27121132, 2016). "Such inhibitors may have applications in clinical indications of DDR1 and DDR2 overexpression or mutation, including lung cancer." (PMID 24768818, 2014). "Several studies have shown the regulatory functions of DDR2 factor in different types of cancers, including lung carcinoma." (PMID 36849997, 2023). "In this study, the AuNP-Apt-based protein delivery system was used to transport peptides containing DDR2 hexahistidine (His) or glutathione S-transferase (GST) labelled transmembrane proximal 1/2 (TM-JM1/2) domain to lung cancer cell lines." (PMID 36741760, 2023). "Although the phosphorylation of DDR2 in lung cancer cell lines was decreased by the administration of dasatinib, the acquired mutation in DDR2 T654I blocked this therapeutic effect." (PMID 37007062, 2023). "We have previously reported that a substantially longer intracellular juxtamembrane region of DDR2 plays a crucial role in DDR2 activation and lung cancer progression." (PMID 28754957, 2017). "According to this analysis, the expression level of DDR2 moderately correlates with overall survival of patients with lung cancer." (PMID 28754957, 2017). "While in A549 lung cancer cells, DDR2 inhibition with siRNA was sufficient to inhibit cell migration induced by TGF-β1." (PMID 27014069, 2016).
lung carcinoma (continued). "Our findings presented in this study have shown that the S768R substitution in the DDR2 gene is detectable not only in patients with primary NSCLC but also in metastatic lesions of lung cancer." (PMID 25173530, 2014). "DDR2 has been shown to promote proliferation in human melanoma, oral squamous cell carcinoma, gastric cancer, hepatocellular carcinoma, lymphoma, and lung cancer among others." (PMID 33917302, 2021). "Finally, we found that the c-Myb–DDR2 axis is crucial for lung cancer cell line proliferation and expression of EMT marker genes in a stiff environment." (PMID 28754957, 2017). "Studies in A549 lung carcinoma cells showed that inhibiting the expression of DDR2 with siRNA is sufficient to alter activity of the NF-κB and the lymphoid enhancer-binding factor 1 (LEF-1) transcription factors and to inhibit EMT and cell migration induced by TGF-β1." (PMID 27014069, 2016). "DNA was also subjected to NGS using the Colon and Lung Cancer Research panel, which allows the assessment of the mutational status of additional genes including DDR2, MAP2K1 and FBX7, which are not covered by the Cancer Hotspot panel." (PMID 26068980, 2015). "We further demonstrate that SHP-2 is phosphorylated by a subset of DDR2 lung cancer mutants." (PMID 23822953, 2013). "Finally, we show that c-Myb silencing may lead to DDR2 inhibition and invasion by lung cancer cells; these effects are reversed by ectopic expression of DDR2." (PMID 28754957, 2017). "This, in turn, increases the accumulation of c-Myb and LEF1 at the DDR2 promoter, resulting in elevated DDR2 expression and facilitating the EMT process in lung cancer cells." (PMID 40563472, 2025). "Discoidin domain receptor 2 (DDR2), i.e., a collagen-induced receptor tyrosine kinase, has recently been identified as a novel therapeutic target for lung cancer." (PMID 36741760, 2023). "This strategy has been further applied to drive to lung cancer cells the functional domain of Discoidin domain receptor 2 (DDR2), a collagen-induced receptor tyrosine kinase that is emerged as a novel therapeutic target in lung cancer." (PMID 27827876, 2016). "Here we report on a spectrum of driver genes, including EGFR, KRAS, c-Met, PIK3CA, BRAF, STK11, PTEN, EML4-ALK fusion gene, DDR2, and FGFR2 in a population of Chinese patients with primary lung cancer." (PMID 22768234, 2012). "In lung cancer cells, increased matrix stiffness triggers activation of lymphoid enhancer binding factor 1 (LEF1) and c-Myb transcription factors and increases discoidin domain receptor tyrosine kinase 2 (DDR2) expression for EMT, invasion, and proliferation." (PMID 35205794, 2022). "Co-activation of MET, AXL, ERBB2, and EPHA2, and co-activation of DDR1 with EGFR, DDR2, HCK, PDGFRA, and FGR is evidence that simultaneous activation of multiple tyrosine kinases may be common in lung cancer." (PMID 23300999, 2013). "However, the regulatory roles of NTRK1 and DDR2 amplification on lung cancer cell behaviors have not yet been characterized." (PMID 36499051, 2022). "Thus, our results suggest that DDR2 regulation by p300 expression and/or c-Myb acetylation upon matrix stiffening may be necessary for regulation of EMT and invasiveness of lung cancer cells." (PMID 28754957, 2017).
lung carcinoma (continued). "DDR2, when activated by type I collagen, was shown to support the migration of human A375 and B16BL6 murine melanoma cells, SK-HEP hepatoma cells, HT-29 colon carcinoma cells, PC-3 prostate cancer cells, A549 lung carcinoma cells, and nasopharyngeal carcinoma cells." (PMID 27014069, 2016). "In addition, DDR2 has not yet been investigated in the context of lung cancer." (PMID 17299390, 2007).
melanoma (23 papers, 2013 to 2026). A malignant, usually aggressive tumor composed of atypical, neoplastic melanocytes. "DDR2 is located on chromosome 1q and has shown to be associated with cell proliferation and survival in multiple cancers including lung, melanoma and hepatoma." (PMID 35887203, 2022). "In human melanoma cells, downregulation of DDR2 is associated with decreased MMP2 and MMP9 activities." (PMID 33917302, 2021). "In various cancers, including bladder, breast, colon, sarcoma, and melanoma, DDR2 knockout increases tumor sensitivity to PD-1 inhibitors." (PMID 40563472, 2025). "In melanoma, DDR2 stimulates tumor proliferation through the MAP kinase pathway, while in lung adenocarcinoma, it enhances cell growth via the focal adhesion kinase (FAK) signaling pathway." (PMID 40563472, 2025). "Intriguingly, DDR2 mediates cell cycle arrest under the treatment of collagen, whereas deglycosylation of collagen can overcome the suppression in melanoma, implying the significance of collagen glycosylation." (PMID 36906534, 2023). "Rather than being expressed in normal tissues, the expression of DDR2 in melanoma cells promotes malignant melanoma growth." (PMID 37007062, 2023). "This group has reported that targeting DDR1 and DDR2 was able to overcome collagen matrix-mediated tumor cell resistance to BRAF-targeted therapy in melanoma." (PMID 37174072, 2023). "The same group also showed that discoidin domain receptors DDR1 and DDR2, which are type I collagen receptors, are able to impact the melanoma cell phenotype." (PMID 37174072, 2023). "The analysis of TCGA datasets for cutaneous melanoma showed that the DDR1 and DDR2 genes were genetically altered in 20% and 13% of melanoma cases, respectively." (PMID 34957688, 2022). "DDR1 and DDR2 are both expressed at different levels in the skin, particularly in the epidermis from which melanoma originates following the malignant transformation of melanocytes." (PMID 34957688, 2022). "Overlapping functions have been attributed to DDR1 and DDR2 in melanoma with regard to cancer cell growth and invasiveness." (PMID 34957688, 2022). "We next examined the levels of DDR1 and DDR2 in a collection of melanoma cell lines and short‐term melanoma cultures in relation to the cell state differentiation markers MITF, SOX10, and AXL." (PMID 34957688, 2022). "Here, we show that DDR1 and DDR2 are key mediators of MMDR in melanoma, through the pro‐survival non‐canonical NF‐κB2 pathway." (PMID 34957688, 2022). "One study showed that, in isogenic murine cancer models, including melanoma, targeting DDR2, using the tyrosine kinase inhibitor Dasatinib, in combination with anti-PD-1, improved therapeutic response to immunotherapy." (PMID 36119516, 2022). "Other studies have reported that DDR2 depletion in melanoma cell lines reduced their invasive and metastatic abilities." (PMID 34957688, 2022). "This matrix-mediated drug resistance was demonstrated to be DDR1 and DDR2 dependent and promoted melanoma cell survival via the NIK/IKKα/NF-κB2 signaling pathway." (PMID 36119516, 2022). "In particular, DDR1/DDR2 induces matrix-mediated drug resistance to MAPKi via activation of the pro-survival NIK/IKKα/NFκB2 pathway in melanoma cells." (PMID 34067929, 2021). "In contrast, melanoma cells require DDR2 expression in the lung metastatic niche and in tumor cells to develop metastatic colonization." (PMID 33917302, 2021). "DDR2 promotes the migration and invasion of metastatic melanoma cells, and DDR2 inhibition makes tumors vulnerable to anti-PD-1 immunotherapy." (PMID 34384498, 2021). "We have previously demonstrated a pro-metastatic role for discoidin domain receptor 2 (DDR2) in A375 melanoma, HT29 colon carcinoma, and SK-HEP hepatocarcinoma cell lines." (PMID 32090682, 2020). "Recently, it has been shown that DDR2 promotes migratory phenotype of B16BL6 murine melanoma cells through the regulation of ERK and NF-κB signaling pathways." (PMID 27014069, 2016).
melanoma (continued). "Nude mice that received intrasplenic injections of human melanoma cell line A375 with stably silenced DDR2 had fewer hepatic metastasis than mice receiving mock transfected cells." (PMID 24505276, 2014). "Activation of DDR2 by fibrillar collagen has previously been shown to inhibit proliferation of human melanoma and fibrosarcoma cells in 2D and 3D assays." (PMID 23822953, 2013). "The enhanced expression of DDR1 and DDR2 collagen receptors in melanoma cells was observed when grown on 3D decellularized ECM from melanoma-related CAFs, in contrast to matrices from regular dermal fibroblasts, highlighting the tumor-enhancing function of CAF-derived ECM." (PMID 40430018, 2025). "Furthermore, inhibition of DDR2 induces decreased invasion of murine melanoma via ERK/NF-κB-mediated MMP secretion." (PMID 36906534, 2023). "The mechanism may be that downregulation of DDR2 in melanoma cells decreases the activity of MMPs to suppress the proliferation, invasion and migration of the cells through inhibition of the ERK1/2 and nuclear factor kappa B (NF-κB) pathways." (PMID 37007062, 2023). "Moreover, B-Raf proto-oncogene (BRAF) mutation (BRAFV600) in melanoma favors collagen-rich environment generated by CAFs, while dual targeting DDR1 and DDR2 contributes to the efficacy of imatinib in vivo." (PMID 36906534, 2023). "Interestingly, a significant fraction of melanomas was found to be associated with an amplification of DNA copy number and higher mRNA levels of DDR1 and DDR2 (respectively 13% and 10% of samples)." (PMID 34957688, 2022). "Importantly, a recent study in melanoma reported that targeting DDR2 with dasatinib enhances tumor response to anti‐PD‐1 immunotherapy." (PMID 34957688, 2022). "Furthermore, it has been reported that MAF-derived matrix enriched of fibrillar and non-fibrillar collagens promotes the clustering of the collagen receptors DDR1/DDR2 into linear membrane structures in melanoma cells." (PMID 34067929, 2021). "Indeed, in vitro inhibition of DDR2 expression results in decreased proliferation in melanoma cell lines via JNK (c-Jun N-terminal kinase) phosphorylation and induction of apoptosis in hepatocellular carcinoma cells." (PMID 33917302, 2021). "On the contrary, DDR2 may also inhibit cell proliferation in melanoma and fibrosarcoma cells in vitro." (PMID 33917302, 2021). "Interestingly, DDR1/DDR2 clustering on the collagen-rich matrix is increased upon melanoma cell treatment with BRAFi." (PMID 34067929, 2021). "Furthermore, DDR2 is able to inhibit proliferation of human melanoma and fibrosarcoma cells by inducing a growth arrest in the G0/G1 phase of the cell cycle when the cells were plated on fibrillar collagen." (PMID 32582700, 2020). "Indeed, DDR2 has been reported to induce an inhibitory effect on proliferation of human melanoma and fibrosarcoma cells, once cultured on fibrillar collagen, with a growth arrest in the G0/G1 phase of the cell cycle." (PMID 27014069, 2016). "Fibroblast-derived ECM protects melanoma cells from BRAFV600-targeted therapies by inducing DDR1 and DDR2 linear clustering." (PMID 41492134, 2026). "Analysis of TCGA databases showed that a significant fraction of melanoma cells strongly expressed DDR1 and DDR2." (PMID 37174072, 2023). "In patient‐derived short‐term melanoma cultures, higher DDR1 and DDR2 protein levels were detected in BRAF mutant MM099 and MM029 and NRAS mutant MM165 cells with the MITFlow, SOX10low, and AXLhigh de‐differentiated phenotype signature." (PMID 34957688, 2022). "The direct interaction of melanoma cells with fibrillar collagen I via DRR1 and DDR2 has also been shown to contribute to melanoma cell migration and invasion." (PMID 36119516, 2022). "For example, one study showed that in murine melanoma cells, the interaction of DDR2 with collagen I resulted in increased expression of MMP2 and MMP9 via the intracellular ERK/NF-κB signaling pathway and promoted melanoma cell invasion." (PMID 36119516, 2022).
melanoma (continued). "Because melanoma and stromal cells also express DDR2, these preclinical studies with DDR1-IN-1 suggest that DDR1, and possibly DDR2, constitutes a potentially new target in melanoma." (PMID 33014862, 2020). "After intrasplenic inoculation, the liver metastasis ability of DDR2-silenced melanoma cells is reduced compared with that of nonsilenced control cells." (PMID 37007062, 2023). "DDR1 and DDR2 were both expressed in melanoma cell lines regardless of their differentiation of cell phenotype." (PMID 34957688, 2022). "In melanoma, a non-cooperative DDR2/intβ1 axis drives matrix-mediated drug resistance." (PMID 41492134, 2026).